MYC (MYC proto-oncogene, bHLH transcription factor)
Diseases named in the same sentence as MYC in open-access papers (continued):
Sharing a sentence is not in itself a finding about the gene and the disease.
neuroblastoma (continued). "Our results strongly indicate that miR-665 upregulation decreased MYC and HDAC8 expression, thus inhibiting proliferation and inducing apoptosis in mouse neuroblastoma cells." (PMID 30237861, 2018). "This is the first report to show that miR-665 is a suppressor miRNA directly targeting the 3’-UTRs of c-MYC and HDAC8 in neuroblastoma." (PMID 30237861, 2018). "Accordingly, our study showed that CX-5461 down-regulated MYC and MYCN proteins and suppressed growth of neuroblastoma cells." (PMID 29464082, 2018). "MYC and HDAC2 repress Cyclin G2 (CCNG2), which ordinarily blocks the progression of the cell cycle, in neuroblastoma and pancreatic cancer cells to drive proliferation." (PMID 28505071, 2017). "The MYCN normal diploid status detected using gDNA was confirmed using cfDNA for the neuroblastoma cell lines, CLB-GA and SK-N-AS, as well as the MYC-amplified medulloblastoma and colon adenocarcinoma cell lines used as controls for MYCN assay specificity." (PMID 29156716, 2017). "Intergenic human snoRNA promoters are enriched in E-boxes which are binding sites for MYC, and in MYCN amplified neuroblastomas, expression of several snoRNAs was reported to be higher compared to non-amplified neuroblastomas." (PMID 29287594, 2017). "It has been shown that MYC upregulates expression of Aurora kinases A and B in neoplasms, and that Aurora kinase A is known to stabilize MYCN protein in neuroblastoma." (PMID 28333115, 2017). "MondoA, a member of the MYC transcriptional network involved in metabolic control, interacts with MYCN to promote neuroblastoma cell survival through the upregulation of metabolic pathways." (PMID 28358317, 2017). "Intriguingly, we have identified destabilization of MYC signaling as an early and consistent feature of ML327 treatment that is observed in both MYCN-amplified and MYCN-single copy neuroblastoma cell lines." (PMID 29207623, 2017). "We also examined the impact of SGO1 knockdown on several neuroblastoma cell lines and found that SGO1 knockdown severely inhibited the proliferation of MYC-amplified cell line (IMR32)." (PMID 27539729, 2016). "TCF7L2 and LEF1 are likely involved in the genesis of neuroblastoma, similar to TCF7L2 driving c-MYC-dependent intestinal tumorigenesis, but subsequently were sharply downregulated in MNA tumours and cell lines from metastatic neuroblastomas." (PMID 27531891, 2016). "Similar to neuroblastoma, SCLC has an etiological link to Myc-family of oncogenes including MYC (c-Myc), MYCN (N-Myc) and MYCL1 (L-Myc)." (PMID 26380220, 2015). "A possible link between MYC/MYCN destabilization and UPR in S(+)-ibuprofen treated neuroblastoma cells is also discussed." (PMID 24173829, 2014). "We have found that S(+)-ibuprofen destabilizes MYC and MYCN proteins in five well-characterized neuroblastoma cell lines." (PMID 24173829, 2014). "Collectively, our results suggest that OSU-03012 affects multiple cellular targets, including Aurora kinase A, to exhibit its growth suppressive and MYC and MYCN-destabilizing effects in neuroblastoma and other cancer cells." (PMID 25017515, 2014). "We next assessed the effect of OSU-03012 and VX-680 on the stability of MYC and MYCN in the neuroblastoma cell lines." (PMID 25017515, 2014). "In this study, we tested the growth suppressive effect of S(+)-ibuprofen, which is also an NSAID, in neuroblastoma cells and investigated the effect of S(+)-ibuprofen on MYCN/MYC expression in these cells." (PMID 24173829, 2014).
neuroblastoma (continued). "In this study, we continued our effort to identify small molecules that can destabilize or downregulate MYC and MYCN protein expression in neuroblastoma cells." (PMID 24173829, 2014). "Further studies are necessary to explore the possible interaction between MYCN/MYC up regulation and SMURF2 copy number gains in neuroblastoma in relation to suppression of TGFβ signaling." (PMID 23308108, 2013). "BMI-1 is a direct transcriptional target of c-MYC and MYCN and is overexpressed in ~90% of neuroblastoma, correlating with MYCN expression." (PMID 23226679, 2012). "The polyamine pathway is frequently deregulated in neuroblastoma, and a number of genes involved in polyamine homeostasis are known to be MYCN or c-MYC targets, while the expression of others is linked to MYCN status." (PMID 23181218, 2012). "This is in agreement with recent demonstrations that high MYC-pathway activity is associated with poor outcome of the disease in neuroblastoma patients, irrespective of whether it was caused by MYCN-amplification, by increased c-MYC level or by any other cause." (PMID 22132187, 2011). "We defined a core set of direct MYCN/c-MYC target genes by applying gene expression profiling and chromatin immunoprecipitation (ChIP, ChIP-chip) in neuroblastoma cells that allow conditional regulation of MYCN and c-MYC." (PMID 18851746, 2008). "From experiments in neuroblastoma cell lines, it is known that MYCN and c-MYC control their expression via autoregulatory loops and via repressing each other at defined promoter sites." (PMID 18851746, 2008). "We further investigated the expression of these direct MYCN/c-MYC target genes in relation to MYCN and c-MYC expression in different clinical neuroblastoma subtypes." (PMID 18851746, 2008). "We also asked whether direct MYCN/c-MYC target genes as defined by our analyses are represented in previously published gene expression-based classifiers that distinguish low-risk from high-risk neuroblastomas independent of other risk markers." (PMID 18851746, 2008). "It is conceivable that in neuroblastoma, MYC-driven transcriptional programs remain more intact or active, particularly in MYCN-negative cases, where C-MYC may act as a compensatory driver." (PMID 41614906, 2026). "In this study, we used two neuroblastoma cell lines: CHLA15 (MYCN non-amplified but MYC-overexpressing) and LAN5 (MYCN-amplified) to investigate the cytotoxic effects of pomiferin and osajin." (PMID 40332068, 2025). "Applying this framework to human brain, liver, and testis promoters, we identified and validated clinically relevant transcription factors (TFs) in the brain, including SP1, MYC, and HES6, and confirmed their known roles in diseases such as gliomas and neuroblastomas." (PMID 41279024, 2025). "Others, like the targeting of the exosome in MYCN‐driven neuroblastoma or CTR9 in PDAC are still to be validated using compounds in vivo, but are still promising targets that promise less toxicity and better drugability than MYC proteins itself." (PMID 40488968, 2025). "Our analysis of ChIP‐seq databases of MYCN‐amplified and c‐MYC‐expressing neuroblastoma cells, suggests that both MYCN and c‐MYC can directly bind the promotor of ATP13A3, though each at different regions, and thus may regulate ATP13A3 mRNA levels." (PMID 39981745, 2025). "Together, these results showed that PA2G4 was required for c-MYC protein stability in these neuroblastoma cell lines, independent of transcriptional regulation." (PMID 41002386, 2025). "Furthermore, c‐MYC also binds the ATP13A3 and ODC1 promoter in neuroblastoma cells, albeit at a different region than MYCN, potentially denoting differences in MYCN and c‐MYC‐mediated regulation of expression." (PMID 39981745, 2025). "Moreover, MYCN and MYC directly influence tumor proliferation and tumorigenesis through BMI1 in human neuroblastomas." (PMID 40862719, 2025).
neuroblastoma (continued). "Taken together with prior studies, our findings in neuroblastoma highlight PA2G4 as a conserved and functionally significant MYC regulatory factor which may have a role in many c-MYC-driven malignancies." (PMID 41002386, 2025). "MYCN-amplified neuroblastoma (MNA neuroblastoma) represents about half of poor prognosis neuroblastoma, with the remainder attributable to enhancer alterations leading to over-expression of TERT or MYC." (PMID 39313128, 2024). "In tumors without MYCN amplification, MYC is overexpressed, further indicating that neuroblastoma is a MYC-driven cancer." (PMID 38488852, 2024). "Alterations in MYC and CCND1 have been frequently observed in bladder cancer, correlating with aggressive phenotypes and worse prognosis, while MYCN alterations were most common in neuroblastomas." (PMID 39410541, 2024). "In contrast to neuroblastoma, we did not observe consistent downregulation of c-MYC in cell lines derived from other nervous system tumors or neonatal dermal fibroblasts." (PMID 37973789, 2023). "The paralog of MYCN, c-MYC, was almost not expressed in our cohort of neuroblastoma patients and thus seemed not to significantly influence circRNA expression." (PMID 37402719, 2023). "In N-MYC-amplified neuroblastoma cell lines, removal of WDR5 from cells also attenuates the ability of N-MYC to bind these same sites, indicating that WDR5 can recruit N-MYC to chromatin at specific regions of the genome as has been seen for c-MYC." (PMID 37336886, 2023). "As for neuroblastoma with hyperactivated RAS activity, YAP might promote the transcriptional activation and expression of E2F and MYC, thereby indirectly mediating trametinib (MEK inhibitor) resistance." (PMID 36619222, 2023). "To establish a suitable model for our study, we first characterized a pair of MYC-amplified therapy-naive CHLA-15 and drug-resistant CHLA-20 neuroblastoma cell lines derived from tumors of the same patient at diagnosis and at relapse after multimodal therapy, respectively." (PMID 37973789, 2023). "Of note, c-MYC, a paralog of MYCN, was almost not expressed in our neuroblastoma cohort, independent of the risk-group." (PMID 37402719, 2023). "Unfortunately, it is currently unknown if WDR5 can recruit N-MYC to chromatin as has been shown for c-MYC, and unclear the extent of overlap between N-MYC and WDR5 in N-MYC amplified neuroblastoma specifically." (PMID 37336886, 2023). "In neuroblastoma, ASCL1 has been described as part of a core regulatory circuit of developmental regulators whose high expression is maintained by mutual cross-activation of a network of super enhancers and is further augmented by the activity of MYC/MYCN." (PMID 36263020, 2022). "MYC is the most broadly deregulated oncogene in a wide range of malignant tumors, whereas MYCN is frequently amplified in neural tumors such as neuroblastoma and small cell lung carcinoma, and MYCL amplifications are solely reported in small cell lung carcinoma." (PMID 35013218, 2022). "Supplementing cystine-deprived cells with either Hcy or Cysta prevented ferroptosis in all adrenergic neuroblastoma cell lines tested with high or intermediate oncogenic MYC(N) expression, but not in the less common mesenchymal neuroblastoma lines." (PMID 35484422, 2022). "MYCMI-7 inhibited cell growth in a MYC-dependent manner, as demonstrated by MYC knockout versus reconstituted Rat1 cells and neuroblastoma cells with or without MYCN amplification." (PMID 36874405, 2022). "Note that non-MYCN–amplified neuroblastoma cells express MYC, albeit at a lower level than MYCN in amplified lines." (PMID 36874405, 2022).
neuroblastoma (continued). "EZH2 is important for neuroblastoma cell survival by suppressing differentiation and tumor suppressors and for stabilizing the MYC oncoprotein, indicating that targeting EZH2 could be an alternative approach for neuroblastoma treatment." (PMID 36612203, 2022). "Depletion, but not enzymatic inhibition, of EZH2 induces robust MYC(N) degradation and inhibits tumor cell growth in MYC(N) driven neuroblastoma and small cell lung carcinoma." (PMID 35013218, 2022). "Since most MYCN-nonamplified neuroblastoma cells exhibited high MYC levels, we also inhibited EZH2 expression in SK-N-AS, SH-SY5Y, and SK-N-SH cells." (PMID 35013218, 2022). "As well as developmental regulators of neurogenesis, the MYC or MYCN oncogenes play a key role in maintaining the high level of cell growth in neuroblastoma tumours; the proliferation of SH-SY5Y cells is supported by MYC and the proliferation of IMR32 is driven by MYCN." (PMID 36263020, 2022). "In MYCN-nonamplified neuroblastomas, high c-MYC levels indicate an identical clinical outcome to that of MYCN-amplified, further proving their functional overlap and establishing c-MYC as a hallmark of an unfavorable course of this cancer type." (PMID 35008802, 2021). "In this study, we found that di-2-pyridylketone 4-cyclohexyl-4-methyl-3-thiosemicarbazone (DpC) potently decreases N-MYC in MYCN-amplified and c-MYC in MYCN-nonamplified neuroblastoma cell lines." (PMID 35008802, 2021). "The genetic and pharmacologic KDM6B inhibition results in a predominant reduction of the E2F transcriptome and MYC, which may account for the therapeutic effect of KDM6B blockade in neuroblastoma." (PMID 34893606, 2021). "DpC treatment significantly decreased MYC protein levels across all neuroblastoma cell lines, which suggests promising new therapy strategies, especially in MYCN-amplified neuroblastomas, which account for approximately 20% of cases and rank among those with the most difficult course of the disease." (PMID 35008802, 2021). "The MYC-driven neuroblastoma group includes both MYCN-amplified and non-amplified tumors with high MYCN and MYC expression, respectively, and they are among the worst tumors that ultimately kill the patients." (PMID 33968044, 2021). "A subset of neuroblastoma cell lines that express high levels of MYC or MYCN does not respond to treatment with retinoids." (PMID 34669465, 2021). "In neuroblastoma cell lines, CDK/CDK1 inhibitors show an ability to downregulate MYC." (PMID 34638300, 2021). "Although MYCN-amplification strongly correlates to poor clinical outcome in neuroblastoma patients, there are no MYC-targeted therapies available in the clinic to date." (PMID 33659885, 2021). "Our data establish the MK2/OCT4/c-MYC axis as a mechanism of progressive disease neuroblastoma regardless of prior to 13-cisRA exposure." (PMID 32409685, 2020). "The importance of MYC expression in neuroblastoma is further emphasized by the fact that neuroblastoma without MYCN gene amplification frequently expressed high levels of C-MYC indicating that C-MYC and N-MYC are mutually exclusive in neuroblastoma." (PMID 33585251, 2020). "Here, we report that intrinsically high MDM2 expression is required for high-level expression of MYCN, but not for expression of MYC, in retinoblastoma, neuroblastoma, small cell lung cancer, and medulloblastoma cells." (PMID 33425720, 2020). "Collectively, these results highlight a complex interplay between c-MYC and MYCN that could regulate radioresistance properties upon glutamine deprivation in neuroblastoma cells." (PMID 32483461, 2020). "Taken together, our results suggest that glutamine deprivation can specifically modulate expression of MYC members and CSC phenotype in neuroblastoma cells and could correspond to the changes in the radioresistant properties." (PMID 32483461, 2020).
neuroblastoma (continued). "To further interrogate how MYCN and/or MYC protein(s) control CAMKV expression, we performed validation CHIP-sequencing for MYCN protein in the MYCN amplified neuroblastoma cell lines: COG-N-415, LA-N-5, NB-1643, and for MYC protein in the MYCN non-amplified lines: NB-69 and SK-N-SH." (PMID 32211329, 2020). "Neuroblastoma, a highly malignant childhood tumor of the sympathetic nervous system, is frequently characterized by MYCN gene amplification and high expression of MYCN and c-MYC signature genes." (PMID 30542116, 2019). "Interestingly, lipid was markedly elevated in all MYC and MYCN amplified neuroblastoma and medulloblastoma." (PMID 29541417, 2018). "Additionally, BET inhibition has most recently been shown to be a potential novel therapeutic strategy for MYC-amplified MB patients and MYCN-amplified neuroblastoma patients." (PMID 29511348, 2018). "In neuroblastoma, ALK activity has been shown to promote transcription of MYCN through phosphorylation of ERK5, a member of the MAPK family, in a PI3K-dependant manner thus integrating ALK effector signaling and MYC regulation." (PMID 29507657, 2018). "Interestingly, specific CDK2 inhibition is found to be synthetically lethal to MYCN-driven neuroblastoma suggesting a potential role for CDK2-inhibiting drugs also in MB-carrying amplifications in MYCN and perhaps also MYC." (PMID 29511348, 2018). "In fact, BMI1 expression, a gene, whose suppression resulted in significantly greater inhibition of cell growth, correlated with MYCN levels in MYCN-amplified neuroblastoma cells, and with MYC levels in the MYCN-nonamplified group." (PMID 30134948, 2018). "Survival of patients with MYC family-driven neuroblastomas where the tumors had MYCN protein (+) and/or MYC protein (+) was significantly worse than that of patients with non-MYC family-driven neuroblastomas where both proteins were (−)/(+/−)." (PMID 29464082, 2018). "In this study, we focused on a subset of unfavorable neuroblastomas with a High-MKI and analyzed the pattern of MYC and MYCN protein expression compared to the distribution of conventional prognostic factors based on their MYCN oncogene status (amplified vs. non-amplified)." (PMID 29464082, 2018). "RNA-Seq expression levels (fragments per kilobase of exon per million fragments mapped (FPKM)) showed high levels of MYC in human Group 3 MB lines D283, sD425, and MB002 and high levels of MYCN in GTML2 cells and in a human neuroblastoma cell line, Kelly, that was also included in the analysis." (PMID 29511348, 2018). "Genes in the two identified prognostic multigene signatures added a new pediatric cancer type, neuroblastoma, to the impacts of the cancer prognostic ESC-like signature showing preferential high-expression of MYC targets combined with low-expression of Polycomb-regulated genes." (PMID 28984200, 2017). "Ruxolitinib was also effective at blocking the macrophage-dependent STAT3 phosphorylation and MYC up-regulation in MYCN non-amplified human neuroblastoma cells." (PMID 29207662, 2017). "There are already several examples of a functional relationship between FACT and MYC proto-oncogene, such that high enrichment of FACT over the body of the MYC gene in chromatin, feed forward interaction between FACT and NMYC in neuroblastoma and potential direct interaction of SSRP1 and c-Myc." (PMID 28423528, 2017). "Specifically, high ABCG2 expression clustered with Group 3 tumors, which was engineered by enforced expression of MYC, likely hinting that MYC might be responsible for the high ABCG2 expression as has been previously reported in CML and neuroblastoma." (PMID 29186899, 2017).